CYTOR (cytoskeleton regulator RNA)
Diseases named in the same sentence as CYTOR in open-access papers (continued):
Sharing a sentence is not in itself a finding about the gene and the disease.
tumor (continued). "Moreover, we also confirmed that genetic depletion of endogenous CYTOR inhibited tumor growth and lymph node metastasis." (PMID 38032139, 2024). "Many of the other lncRNAs, such as LINC01220, CYTOR, LINC00910, LINC00511, PURPL, and MZF1-AS1, have been described in association with different types of cancer, mainly with proliferation and migration of the tumour cells." (PMID 38616192, 2024). "CYTOR showed a significantly higher expression in tumor samples than in normal tissues (P<0.05)." (PMID 38911384, 2024). "Surprisingly, CYTOR showed a significantly high expression in circulating tumor cells." (PMID 38911384, 2024). "CYTOR was found to be expressed at high levels in circulating tumor cells." (PMID 38911384, 2024). "Compared with the sh-NC group, sh-CYTOR-1 and sh-CYTOR-2 could inhibit tumor growth, while pc-CYTOR accelerated tumor growth." (PMID 35081873, 2022). "Sh-CYTOR could induce cell apoptosis and inhibit cell proliferation, and effectively inhibited tumor in mice, and the results of pc-CYTOR were reversed in in vivo experiments." (PMID 35081873, 2022). "In light of these findings, we then explored the Enhanced Permeability and Retention (EPR) effects of nanoparticle accumulation at tumor sites by synthesizing nanoscale metal-organic frameworks (NMOFs) to package siRNAs targeting CYTOR for suppression in an in vivo OSCC mouse model." (PMID 35963855, 2022). "Like our analysis, LINC01554 may function as a tumor suppressor gene, while the CYTOR and BSG-AS1 may act as oncogenes." (PMID 35840618, 2022). "Furthermore, CYTOR contributed to cell proliferation in vitro and tumor growth in vivo via EGFR-mediated PI3K/AKT pathway." (PMID 29108264, 2017). "Moreover, tumor growth was also repressed by CYTOR knockdown as shown in the tumor growth curve." (PMID 30064438, 2018). "Additionally, CYTOR could promote cell proliferation in vitro and tumor growth in vivo via activating the mTOR (mechanistic target of rapamycin) signaling pathway." (PMID 29108264, 2017). "The expression of CYTOR and its methylation in SKCM tumor tissues was analyzed by qRT-PCR and used to predict the prognosis and immunotherapy response of SCKM patients." (PMID 38911384, 2024). "The ability of tumor sphere formation was significantly decreased in SCC1 and HN6 cells with depletion of CYTOR but enhanced in CAL33 and SCC15 cells overexpressed CYTOR." (PMID 38032139, 2024). "CYTOR ASO treatment significantly reduced tumor volume and tumor weight compared with the control ASO in the HNSCC subcutaneous xenograft models." (PMID 38032139, 2024). "CYTOR (synonymous with C2orf59, LINC00152, and NCRNA00152) is a long noncoding RNA that is overexpressed in tumor cells and promotes cell proliferation and the epithelial-mesenchymal transition." (PMID 36814556, 2023). "Further studies had shown that CYTOR and MSC-AS1inhibited the apoptosis of tumor cells and promoted EMT and tumor proliferation by acting as the ceRNAs for the miRNAs, such as miR-4775, miR-125B-5P." (PMID 36036006, 2022). "Among the downregulated genes in LA-treated cells were RGCC, a cell cycle regulator; CYTOR, a long non-coding RNA that enhances proliferation; and CEACAM6, which is a cell adhesion molecule that promotes tumor progression." (PMID 33546321, 2021). "Previously, we found through laser microdissection capture in CRC tissues that a novel lncRNA, CYTOR (also known as LINC00152), was up-regulated in tumor budding cells." (PMID 30064438, 2018). "Our previous expression profile data showed that CYTOR was up-regulated in CRC and tumor budding cells." (PMID 30064438, 2018). "Our results showed that the relative expression levels of CYTOR and PVT1 were up-regulated, while HAR1A and MIAT were significantly down-regulated in diffuse glioma specimens compared to non-tumor tissues (all P <0.001)." (PMID 29108264, 2017).
tumor (continued). "Subsequent analyses demonstrated that the expressions of PVT1 and CYTOR were up-regulated, while HAR1A and MIAT were down-regulated in diffuse glioma samples compared to non-tumor tissues." (PMID 29108264, 2017). "Of note, the extreme limited dilution assay showed that capacities of tumor sphere formation were significantly suppressed in SCC1 and HN6 cells by depletion of CYTOR and increased in CAL33 and SCC15 cells with overexpression of CYTOR." (PMID 38032139, 2024). "Furthermore, the effects of miR-873-5p and CYTOR on THCA were divergent from those produced by other tumors identified in the literature review, possibly due to the prominent tumor heterogeneity of THCA." (PMID 36060256, 2022). "In the present study, we showed that CYTOR was significantly up-regulated in NSCLC tissues, and high-level CYTOR expression correlated with larger tumor size, advanced TNM stage, lymph node metastasis and poor prognosis, suggesting that CYTOR can be a strong predictor for NSCLC progression." (PMID 30487160, 2018). "Thus, CYTOR may exhibit high differential expression in SKCM, especially in circulating tumor cells, and may be used for the diagnosis of SKCM." (PMID 38911384, 2024). "Comparing CYTOR expression in tumors with adjacent noncancerous tissue using qPCR demonstrated that CYTOR was significantly upregulated in OSCC tissue (Normal, 8.339 ± 1.942 vs Tumor, 9.423 ± 2.098; P = 0.0002, n = 63)." (PMID 35963855, 2022).
cancer (76 papers, 2015 to 2025). A tumor composed of atypical neoplastic, often pleomorphic cells that invade other tissues. "The lncRNA LINC00152, also known as CYTOR, which is encoded on human chromosome locus 2p11.2, is upregulated in cancer cells and facilitate cell proliferation as well as epithelial-mesenchymal transition." (PMID 33842324, 2021). "Long noncoding RNA (lncRNA) LINC00152 (CYTOR) has been reported to be upregulated and to serve as a diagnostic biomarker in multiple types of cancers, including laryngeal squamous cell cancer (LSCC)." (PMID 32266320, 2020). "CYTOR as a non-coding RNA usually plays the role of an oncogene in cancer, but it can also regulate cell growth in normal cells." (PMID 39058104, 2024). "Taken together, these findings indicate that CYTOR is involved in cell migration, invasion and stemness, which is required for a metastatic phenotype of cancer cells." (PMID 38032139, 2024). "The transcription factor SP1 promotes the expression of CYTOR, which, in turn, promotes the metastasis of cancer cells through the PI3K/AKT pathway." (PMID 39058104, 2024). "CYTOR downregulation inhibits the invasiveness of cancer cells in vitro and in vivo by interacting with miR-139-5p." (PMID 36814556, 2023). "Further studies are needed to investigate different possible modes of CYTOR targeting (and consequently, energy metabolism) for anti-cancer therapies." (PMID 35963855, 2022). "Our findings here and in previous studies of cancer cell energy metabolism led us to propose that the CYTOR lncRNA can act as a regulator of both mitochondrial respiration and glycolysis in OSCC." (PMID 35963855, 2022). "The nude mouse model for lung metastases inoculated with CYTOR-expressing cancer cells showed that the CYTOR knockdown group had a decrease in the size and number of metastatic tumor nodules compared with the control group." (PMID 34778084, 2021). "The long noncoding RNA (lncRNA) LINC00152, also known as CYTOR, displays aberrant expression in various cancers." (PMID 33842324, 2021). "CYTOR is broadly expressed in fetal and adult tissues, with low levels in adult and fetal brain, and is overexpressed in cancer cells." (PMID 32780866, 2020). "LINC00152, also known as CYTOR (long non-coding RNA cytoskeleton regulator RNA), was recently identified as a cancer-related lncRNA that plays oncogenic roles in several types of cancer." (PMID 32183133, 2020). "The aberrant expression of CYTOR was observed in some types of cancers, such as colorectal cancer, glioblastoma and gallbladder cancer, in which it functioned as an oncogenic lncRNA." (PMID 30487160, 2018). "CYTOR acts as a novel putative onco-lncRNA, which was overexpressed in many cancer types and promoted growth and metastasis." (PMID 30487160, 2018). "A decreased expression of cytoplasmic CYTOR was observed in TB cells than in cancer cells from TC." (PMID 38032139, 2024). "Moreover, cancer cells with moderated or poor differentiation had higher expression of CYTOR than the well differentiated cells." (PMID 38032139, 2024). "We therefore hypothesized that HNRNPC may specifically interact with CYTOR to positively regulate cancer cell metabolism." (PMID 35963855, 2022). "CYTOR can modulate multiple signaling pathways in cancer cells." (PMID 35954207, 2022). "Given its crucial role in the pathogenesis of cancers, CYTOR (average fold change = 3.40, Δ percentage =95%) may play a role in SPTCL development." (PMID 33816243, 2021). "Among these 9 unique directly-related-to-cancer lncRNAs, only CYTOR and SNHG12 have Wilcoxon test p-values < 0.05 and may be loosely regarded as differentially expressed genes between LSCC and HSCC subtypes, and between cancer tissues and normal tissues." (PMID 32024523, 2020). "CYTOR also plays a role in the regulation of many cancer types by acting as a ceRNA." (PMID 30487160, 2018). "The lncRNA CYTOR plays oncogenic roles in multiple types of cancer, yet the detailed molecular mechanisms of those roles remain unknown." (PMID 30064438, 2018).
cancer (continued). "Notably, TB cells had higher total and nuclear CYTOR expression than cancer cells in TC and/or LNM." (PMID 38032139, 2024). "However, ncRNAs that regulate key cellular pathways, such as CYTOR, might be hijacked by cancers." (PMID 39960339, 2025). "Of the four lncRNAs included in the lncRNA-based classifier, CYTOR (Ensembl ID: ENSG00000222041) is a well-studied lncRNA on chromosome 2, which acts as an oncogene in many cancers." (PMID 39043664, 2024). "Depletion of CYTOR leads to the disruption of FOSL1‐dependent SEs, which results in the inactivation of cancer stemness and pro‐metastatic genes." (PMID 38032139, 2024). "Others, such as LINC01220, CYTOR, LINC00910, LINC00511, PURPL, and MZF1-AS1, have been described so far only in cancer." (PMID 38616192, 2024). "GSEA identified that the EMT, mammary stem cell, cancer stemness, and FOSL1 target gene sets’ expression levels were all significantly inhibited by knockdown of CYTOR in SCC1 and HN6 cells." (PMID 38032139, 2024). "The lncRNA cytoskeletal regulatory RNA (CYTOR), also known as LINC00152, is located in the chromosomal region 2p11.2, and is overexpressed in many cancers." (PMID 36033524, 2022). "The biofunction “development of carcinoma” was one of the top cancer-related enriched biofunctions (p-value of 0.0176), with 8 DE lncRNAs: PVT1, CASC2, PCA3, EPB41L4A-AS1, C10orf25, CYTOR, FOXD2-AS1, and CRNDE." (PMID 33926464, 2021). "The increased expression of PVT1, CYTOR, FOXD2-AS1, and CRNDE were seen in various cancers, similarly these lncRNAs were all up-regulated in G-CIMP-low suggesting their more oncogenic activity leads to poor prognosis compared to G-CIMP-high." (PMID 33926464, 2021). "miR-3679-5p seems to activate the cytoskeleton regulator RNA (CYTOR), which plays a pivotal role in the development and progression of a variety of cancers." (PMID 32019170, 2020). "For LSCC prognostic lncRNAs, H19, MALAT1, NEAT1, CYTOR and SNHG12 were ranked as the first five of this directly-related-to-cancer list." (PMID 32024523, 2020). "While no direct connection between camptothecin and CYTOR has been previously reported, these findings suggest that in cancers where the PI3K/PKB pathway and CYTOR are highly active, camptothecin may have its most potent anticancer activity." (PMID 40308216, 2025). "We then examined the expression levels of the corresponding mRNAs in 10 paired clinical samples, in which LNC000894, VPS9D-AS1, and CYTOR were highly expressed in cancer, while LNC000460 and FOXD2-AS1 were not evident." (PMID 36104748, 2022). "The upregulation of CYTOR accelerates β-catenin nuclear translocation and increases the transcription activity of the β-catenin/TCF complex in the nucleus, activating the Wnt/β-catenin pathway to promote cancer cell invasion and metastasis." (PMID 34778084, 2021). "It was found in the LncTarD database that CYTOR functioned as a competing endogenous RNA (ceRNA) to positively regulate NRP1 expression by sponging with miRNA-206, which could positively affect epithelial to mesenchymal transition, cancer progression, and cell growth." (PMID 33749514, 2021).
infection (2 papers, 2019 to 2022). The state of being infected such as from the introduction of a foreign agent such as serum, vaccine, antigenic substance or organism. "To further assess its function, we established stable CYTOR knockdown (KD) and overexpression (OE) cell lines via lentiviral infection of HN6 and Cal27 cells." (PMID 35963855, 2022). "In contrast, CYTOR, FOXD3-AS1, and MALAT1 were consistently downregulated during the infection." (PMID 31547203, 2019).
CYTOR also shares sentences with these, for which no sentence is quoted: lung carcinoma (9 papers); bladder cancer (5); esophageal cancer (4); oral squamous cell carcinoma (4); clear cell renal cell carcinoma (3); esophageal squamous cell carcinoma (3); osteosarcoma (3); ovarian carcinoma (3); rheumatoid arthritis (3); acute myeloid leukemia (2); cholangiocarcinoma (2); multiple myeloma (2); prostate carcinoma (2); stomach cancer (2); anaplastic large cell lymphoma (1); atherosclerosis (1); bacterial infection (1); benign tumors (1); brain tumor (1); cardiovascular disorder (1); cervical cancer (1); colon adenocarcinoma (1); colorectal (1); endometrioid carcinoma (1); epilepsy (1); gastric adenocarcinoma (1); hemangioma (1); liver diseases (1); low grade glioma (1); lung squamous cell carcinoma (1).
A further 11 diseases each share a sentence with CYTOR in 1 paper.